TNF (tumor necrosis factor)
Diseases named in the same sentence as TNF in open-access papers (continued):
Sharing a sentence is not in itself a finding about the gene and the disease.
hearing loss (continued). "The effect of Tnfα gene silencing on the expression profile related to the TNFα metabolic pathway in an experimental model of noise-induced hearing loss had not previously been studied." (PMID 32294929, 2020). "Furthermore, Uchida and co-authors reported a possible involvement of the signalling cascades of tumour necrosis factor-α (TNF-α) in hearing impairment." (PMID 28404559, 2017). "The pathophysiology is unknown, but several studies showed that the signalling cascades of TNF are involved in hearing impairment." (PMID 28404559, 2017). "Given that elevated levels of TNF-α and TWEAK are associated with the greater severity of human hearing loss, and that these factors are increased in the perilymph on the tumor-bearing side, it is plausible to propose their cooperation in mediating VS-induced hearing loss." (PMID 39923035, 2025). "Serum concentrations of TNF-α and C-reactive protein (CRP) are significantly increased in people with hearing impairment under the age of 60." (PMID 34320993, 2021). "Using the criterion of PTABE >40 dB as disabling hearing impairment, the association remains significant in TNFRSF1B rs1061624, but not in TNF-α rs1800630." (PMID 25469152, 2014).
irritable bowel syndrome (36 papers, 2011 to 2025). Irritable bowel syndrome (IBS) is a chronic functional condition of the lower gastrointestinal (GI) tract characterized by abdominal pain or discomfort and disordered bowel habit (diarrhea, constipation, or fluctuation between the two). "IgA antibody responses to enteric bacteria in ME/CFS patients have to date been associated with higher serum IL-1, TNFα, and neopterin levels, autoimmune responses to serotonin, and increased symptoms of irritable bowel syndrome." (PMID 26683192, 2015). "lactate V9) as adjuvant therapy for irritable bowel syndrome significantly reduced serum levels of inflammatory cytokines (IL-6 and TNF-α) in patients." (PMID 40284709, 2025). "Conversely, CDCA previously given to patients with irritable bowel syndrome increased the presence of inflammatory markers in the terminal ileum, including IL-6 and TNF-α." (PMID 34452145, 2021). "And compared to control rats and enteric glial cells, the expression levels of GFAP, S100B, SP, CGRP, TRPV1, TNF, IL-1β, and IL-6, were significantly higher in the colonic tissues of irritable bowel syndrome (IBS) rats and lipopolysaccharide (LPS)-treated EGCs." (PMID 40225339, 2025). "Additionally, Romboutsia proliferates in gastrointestinal disorders, including irritable bowel syndrome, and its levels is positively correlated with pro-inflammatory cytokines, such as TNF." (PMID 40574855, 2025). "Veillonella levels have been found to be higher in patients with irritable bowel syndrome, and the lipopolysaccharide (LPS) produced by Veillonella could stimulate the release of TNF-α, IL-1, IL-6 and IL-10 within Toll-like receptor (TLR) pathways." (PMID 37208752, 2023). "The increase in pro-inflammatory cytokines such as TNF-α, may also depict the presence of an inflamed gut or irritable bowel syndrome in some CFS/ME patients." (PMID 21619669, 2011). "Bifidobacterium longum ES1 significantly reduces serum levels of IL-6, IL-8, and TNF-α in patients with irritable bowel syndrome (IBS), while restoring intestinal permeability and barrier function." (PMID 41299994, 2025). "SP stimulates the synthesis of TNF-α, IL-1β, and IL-6 in the human colonic mucosa, increases the production of IL-1β and IL-6 mRNA in human glial cells, and co-operates with mast cells in the wall of ileum and ascending colon of irritable bowel syndrome (IBS) patients." (PMID 33353157, 2020). "OSM and TNF-α are inflammatory cytokines elevated in CDI and irritable bowel syndrome (IBD)." (PMID 36557633, 2022). "Many studies had explored ideal predictors for primary nonresponders in patients with irritable bowel syndrome receiving anti-TNFα therapy." (PMID 35517818, 2022). "Calprotectin may be used as a biomarker in cases of suspected IBD, in differentiation from irritable bowel syndrome (IBS), in monitoring of disease activity, predicting remission, monitoring response to anti-TNFα therapy, and detecting postoperative recurrence in CD." (PMID 39062093, 2024).
Pleural effusion (36 papers, 1997 to 2025). The presence of an excessive amount of fluid in the pleural cavity. "In our study, using multivariate logistic regression, VEGF [odds ratio (OR): 2.46, P = 0.01], TNF-α (OR: 3.64, P = 0.04), and C3 (OR: 3.77, P = 0.02) levels were identified as the independent risk factors for pleural effusions." (PMID 37993859, 2023). "The study established cutoffs with considerable predictive and diagnostic value for Tb with pleural effusions: 4000 pg/mL for IL-6 (sensitivity: 90.6%; specificity: 76.5%), 4 pg/mL for TNF-α (sensitivity: 90.6%; specificity: 79.4%), and 60 pg/mL for IFN-γ (sensitivity: 100%; specificity: 100%)." (PMID 28487810, 2017). "IL-6, IL-8, IL-10, TNF (p<0.0001) levels were significantly higher in pleural effusion compared to plasma." (PMID 39737183, 2024). "Instead, pleural effusion has been reported in patients treated with TNF inhibitors such as infliximab and etanercept." (PMID 39744302, 2024). "Recent investigations have demonstrated that the C1q levels in pleural effusion can differentiate tuberculous pleural effusion (TPE) from non-TPE26, 27, exhibiting higher diagnostic accuracy than tumor necrosis factor (TNF)-α and IL-6." (PMID 39664577, 2024). "In a pooled analysis of all 19 trials, the results revealed that there was a significant increase in the pleural effusion levels of TNF-α in TPE subjects compared to MPE subjects [2.22, (1.60–2.84, p < 0.00001)]." (PMID 35177742, 2022). "In the pleural effusion of mice receiving intrapleural injection, the levels of TNF-α (P = 0.0004) and IL-1β (P = 0.0422) were significantly higher than those of the NS group." (PMID 34966384, 2021). "Our patient is unique as few cases of anti-TNF-α-induced pleural effusion and pericarditis in CD are reported." (PMID 34336341, 2021). "There are few reports about the IL-2, IL-6, and TNF-α levels in pleural effusions of patients with tuberculous pleurisy and tuberculous empyema." (PMID 27034588, 2016). "In our study the TNF-α levels in the pleural effusion of patients with tuberculous pleurisy and tuberculous empyema had no statistical difference, as well as the two groups of tuberculous empyema." (PMID 27034588, 2016). "The clinical data in the present study demonstrate the elevated effusion levels of TNF-α, MMP-1 and MMP-9 in TBP and the association of these mediators with amount of pleural effusion and area of pleural fibrosis." (PMID 26367274, 2015). "Several studies have reported that TPE is a Th1-dominant environment, and that Th1 cytokines such as IFN-γ and TNF-α predominate at pleural effusions in patients with TPE." (PMID 22889060, 2012). "The origin of foamy macrophages is attributed to the ensuing inflammatory response, with roles for interferon gamma (IFNγ), tumor necrosis factor alpha (TNFα), lipids in the pleural effusion and necrotic milieu being identified as relevant players across host species." (PMID 34603294, 2021). "Therefore, we confirmed that TNF-α could be used for discriminating diagnosis of pleural effusions, from TB and malignant outcomes." (PMID 24984978, 2014). "The development of a pleural effusion in immunocompetent hosts is associated with an intense cell-mediated immune response with infiltration of CD4 T cells and production of high levels of proinflammatory cytokines such as gamma interferon (IFN-) and tumor necrosis factor alpha (TNF-α)." (PMID 22474483, 2012). "Using the Luminex system to analyze Th1/Th2 cytokines in pleural effusion, we found that Th1 cytokines, including TNF-α, IFN-γ, and IL-12, were significantly lower in the MPE of LCP compared to the pleural effusion of HP." (PMID 40959273, 2025). "Alterations in cytokine profiles, including high tumor necrosis factor (TNF)-α, IL-6, and IL-1 levels and low interferon-γ levels, are common in both pleural effusion and RA." (PMID 39744302, 2024).
Pleural effusion (continued). "Tuberculous pleural effusions are characterized by enhanced MAIT cells expressing IFNγ and TNFα compared to periphery and after stimulation with Bacillus Calmette-Guerin (BCG)." (PMID 35056035, 2022). "The concentration of cytokines (IL-6, TNFα, IFNɤ, MCP-1, IL-2) in pleural effusion were higher in mice in the BCG + SiCon group than in the PBS + SiCon group, which is consistent with previous studies." (PMID 30669315, 2019). "TNF-α, VEGF, and IFN-γ levels are increased at pleural effusions in patients with TPE, suggesting a role for these cytokines in the immune response to mycobacterium infection." (PMID 22889060, 2012). "The release of IFN-γ and TNF-α by CD8+ and Th1 cells triggers alveolar epithelial and endothelial apoptosis, promoting interstitial fibrosis with minimal pleural permeability increase, leading to infrequent pleural effusions." (PMID 40458408, 2025). "In contrast to the first phase of pleural effusions around day 30, there were also relevant increases in NT-proBNP, CK, CRP as well as several chemokines and pro-inflammatory cytokines, like MCP-1, I-TAC, MIG, IL-6, IL-12, TNF-α and eotaxin." (PMID 39200391, 2024). "Likewise, levels of PAI‐1, TNF‐α, TGF‐β, IL‐8 in loculated/complicated pleural effusions in humans are higher than those in transudate/free flowing ones." (PMID 33991465, 2021). "Ruxolitinib but not anti-TNF antibody prevented hypothermia and terminal disease as well as pleural effusions and skin edema, which served as readouts of microvascular leak." (PMID 33803310, 2021). "We screened pleural effusions for mediators thought to interfere with fibrogenesis (transforming growth factor-β (TGF-β), tumour necrosis factor α (TNFα), soluble TNF-receptor p55 (sTNF-R)) and correlated the results with patient clinical outcome in terms of extent of pleural thickenings." (PMID 18472845, 1997). "We aimed to examine whether the interleukin-1β (IL-1β), IL-2, IL-6, tumor necrosis factor-α (TNF-α), plasminogen activator inhibitor type-1 (PAI-1), and tissue plasminogen activator (t-PA) levels were different in pleural effusions of tuberculous pleurisy and tuberculous empyema." (PMID 27034588, 2016). "The aim is to examine whether the interleukin-1β (IL-1β), IL-2, IL-6, tumor necrosis factor-α (TNF-α), plasminogen activator inhibitor type-1 (PAI-1), and tissue plasminogen activator (t-PA) levels were different in pleural effusions of tuberculous pleurisy and tuberculous empyema." (PMID 27034588, 2016).
systemic sclerosis (36 papers, 2008 to 2025). A chronic disorder, possibly autoimmune, marked by excessive production of collagen which results in hardening and thickening of body tissues. "In this context, it is of note that cytokine signatures, including TNFα, differentiate systemic sclerosis (SSc) patients at high versus low risk for PAH." (PMID 35742956, 2022). "The aim of the study was to establish an association between TNF-α promoter variability and systemic sclerosis (SSc)." (PMID 35629365, 2022). "It appears plausible that suPAR is positively regulated by TNF-α in systemic sclerosis, as the levels of these molecules are mutually correlated." (PMID 40362179, 2025). "Both IL-6 and TNFα are also being evaluated in clinical trials as potential drug targets for the treatment of systemic sclerosis." (PMID 37228128, 2023). "In vitro treatment of ibrutinib in peripheral blood from systemic sclerosis reduces IL-6 and TNF-α production, while IL-10 is preserved." (PMID 36521376, 2022). "Previous studies have indicated that serum TNF-α levels were positively correlated with leptin levels in patients with systemic sclerosis." (PMID 32265847, 2020). "Several TNF-α inhibitors have been shown to significantly improve the condition of patients with systemic sclerosis." (PMID 33329519, 2020). "Finally, in systemic sclerosis, TNF-α was found to be elevated in SSc patients, and its higher serum levels, influenced by specific TNFA gene promoter polymorphisms, correlate with an increased risk of cancer in these patients." (PMID 41009491, 2025). "Among these cytokines, only TNF-α levels were significantly elevated in patients compared to controls and were also higher in the diffuse systemic sclerosis (dcSSc) group compared to the limited systemic sclerosis group." (PMID 40362179, 2025). "In in vitro experiments using peripheral blood from patients with systemic sclerosis, ibrutinib reduced the production of pro-fibrotic cytokines IL-6 and tumor necrosis factor-α, while preserving the inhibitory role of IL-10, which helps suppress the overactivation of fibrotic functions in B cells." (PMID 39280007, 2024). "Moreover, the knockdown of STAT4 protected the bleomycin-injected mice from the development of systemic sclerosis via reducing the T cell infiltration and the cytokine levels of tumor necrosis factor-alpha (TNF-α), IL-6, IL-2, and INF-γ." (PMID 34258301, 2021). "Inflammatory mediators like TNF-α found at the lesioned site of systemic sclerosis patients have also been reported to play a vital role in SSc." (PMID 37371141, 2023). "M1 macrophages stimulate an inflammatory reaction by triggering cytokines such as TNF-α and IL-6, resulting in Th1 reactivity, whereas BD patients with skin lesions conferred M1 macrophage dominance in systemic sclerosis (SSc)." (PMID 34975900, 2021). "Similarly, high levels of TNF-α can be detected in patients with systemic sclerosis." (PMID 33329519, 2020). "PBC: primary biliary cholangitis; SSc: systemic sclerosis; TGF-β: transforming growth factor-beta; IL: interleukin; TNFα: tumor necrosis factor-alpha; EBV: Epstein-Barr virus; CMV: cytomegalovirus." (PMID 40351968, 2025). "In systemic sclerosis (SSc), IL-22 synergistically works with TNFα to induce the expression of IL-8 and CCL2 in skin fibroblasts, while the simultaneous stimulation of TGF-β1 and IL-17A can lead to an up-regulation of IL-6 expression in fibroblasts from affected skin by nearly a hundredfold." (PMID 35967331, 2022). "Additionally, TNF-α induces IL-6 and CCL2 secretion by systemic sclerosis fibroblasts, thereby enhancing their activation and differentiation into myofibroblasts perpetuating inflammation and fibrosis." (PMID 41155396, 2025).
systemic sclerosis (continued). "In vitro studies exhibited that fibroblasts from systemic sclerosis patients express high levels of α-SMA and CAMs (αvβ3 and αvβ5 integrin) that leads to sustained activation of the TGF-β pathway, as well as proinflammatory and chemotaxis cytokines such as IL-6, TNF-α, IL-1α, IL-1β, and MCP-1." (PMID 34258301, 2021). "When searching for “systemic sclerosis” and cytokines in the PubMed database, TGF-β had the highest number of hits, followed by IL-6, IL-4, tumor necrosis factor (TNF)-α, platelet-derived growth factor, IL-10, IL-13, IL-1, IL-2, and IL-17 indicating cytokines are related to the pathogenesis of SSc." (PMID 34064515, 2021).
coronary atherosclerosis (35 papers, 2009 to 2025). Atherosclerosis of the coronary vasculature. "Tumor necrosis factor-alpha (TNF-α) and interleukin-6 (IL-6) are significantly associated with coronary atherosclerosis." (PMID 19551157, 2009). "The cause of coronary artery atherosclerosis develops on the basis of inflammation, with a concomitant increase in prothrombotic activity and the release of proinflammatory cytokines, including interleukin 2 and interleukin 6 and tumor necrosis factor alpha." (PMID 39684812, 2024). "An increased activation of circulating monocytes has been reported in patients receiving anti-TNF therapy and the elevations of monocyte subpopulation can be seen in RA patients with coronary artery atherosclerosis and are associated with an increased CVD risk." (PMID 34344436, 2021). "Clinical studies have shown that the interaction between TNF-α and oxidative stress is related to the severity of coronary atherosclerosis and can be used as a potential noninvasive diagnostic organism for coronary chronic total occlusions (CCTO) in elderly patients with CHD landmark." (PMID 34887932, 2021). "Moreover, TNF-α and IL-6 are important pro-inflammatory factors that promote the accumulation of immune complexes in endothelial cells, which increase the risk of thrombosis and participate in the vascular inflammatory response and coronary atherosclerosis." (PMID 40584629, 2025). "Other agents, such as TNF inhibitors, have shown potential in preventing coronary atherosclerosis by targeting inflammatory pathways." (PMID 40003654, 2025). "One recent study characterized coronary atherosclerosis as the concomitance of macrophage polarization with a greater expression of interleukin-6, tumor necrosis factor-alpha and monocyte chemotactic protein-1." (PMID 37380905, 2023). "ACR elevates the levels of tumor necrosis factor-α (TNF-α) in endothelial cells and plays a key role in coronary atherosclerosis." (PMID 33936387, 2021). "In fact, activation of NF-κB is implicated in pathological inflammation, promoting the transcription of pro-inflammatory cytokines, such as TNF-α and IL-6, which are involved in the progression of coronary atherosclerosis." (PMID 32640692, 2020). "Toll-like receptor 4 (TLR4) activation promoted inflammatory response and oxidative stress and was involved in regulating proinflammatory cytokine TNF-α through its key role in coronary atherosclerosis." (PMID 31780868, 2019). "TNF-α is a pro-inflammatory cytokine also considered as a pro-atherogenic factor and high levels have been found in patients with coronary atherosclerosis." (PMID 31500172, 2019). "In another study called SIRCA (Study of Inherited Risk of Coronary Atherosclerosis), circulating leptin was associated with inflammatory factors (IL-6, CRP, and TNF-α) and also represented an independent marker for coronary artery calcifications." (PMID 24616817, 2014). "Future studies to probe mechanisms will include blockade of VCAM-1, TNFα or IL-6 or depletion of neutrophils to examine the extent to which increased VCAM1, TNFα, IL-6 and neutrophilia with advanced age drives the increased burden of coronary artery atherosclerosis." (PMID 40403091, 2025). "It is plausible that TNAP-driven calcification in our in vivo model might also increase secretion of CPP and promote inflammation via upregulation of TNFα that in turn could explain the excess of coronary atherosclerosis in WHC-eTNAP mice." (PMID 29023576, 2017). "Moreover, Luo J G and colleagues investigated the relationship between serum hsCRP and TNFα levels and severity of coronary atherosclerosis in 100 patients." (PMID 24757644, 2014). "However, genetic liability to IL-1, interleukin 8, interferon-β and TNF-α had no potential causal effect on coronary atherosclerosis (All P > 0.05)." (PMID 37187788, 2023).